CD248 (CD248 molecule)
Diseases named in the same sentence as CD248 in open-access papers (continued):
Sharing a sentence is not in itself a finding about the gene and the disease.
liver fibrosis (continued). "IHC staining showed that CD248 levels were markedly upregulated in liver fibrosis (p < 0.0001)." (PMID 35317721, 2022). "Given that IgG78-DM1 could effectively kill CD248+ HSCs in vitro, we next examined whether it could alleviate liver fibrosis in vivo." (PMID 35317721, 2022). "IgG78-DM1 was successfully generated, which could effectively bind with and kill CD248+ activated HSCs in vitro and inhibit liver fibrosis in vivo." (PMID 35317721, 2022). "However, CD248 expression is upregulated on activated HSCs during liver fibrosis, while in Cd248 knockout mice, CCl4-induced liver fibrosis was obviously alleviated and the expression of collagen I, α-SMA, and TGF-β were all inhibited significantly." (PMID 35317721, 2022). "In this study, we have identified CD248 as a novel therapeutic target in liver fibrosis." (PMID 26078290, 2016). "After 4 weeks resolution, WT and CD248−/− mice had similar levels of liver fibrosis." (PMID 26078290, 2016). "Later studies showed that CD248 expression was also upregulated specifically in liver fibrosis, and CD248 was expressed mainly in activated HSCs, but not in quiescent HSCs, indicating that CD248 could be an effective therapeutic target for liver fibrosis." (PMID 35317721, 2022). "Thus, CD248 was confirmed to be specifically expressed on activated HSCs and could be used as a target to treat liver fibrosis." (PMID 35317721, 2022). "The primary aim of this study was to generate a CD248 specific antibody-drug conjugate (ADC) and evaluate its therapeutic efficacy for liver fibrosis and its safety in vivo." (PMID 35317721, 2022). "In addition, CD248 is expressed on the cell surface, and therefore CD248-positive stromal cells could be a potential target for the modulation of liver fibrosis using novel antiangiogenic drugs such as the antihuman CD248 monoclonal antibody MORAb-004,21 currently in clinical trials in cancer." (PMID 26078290, 2016). "Our study demonstrated that CD248 could be an ideal target for myofibroblasts in liver fibrosis, and CD248-targeting IgG78-DM1 had excellent anti-fibrotic effects in mice with liver fibrosis." (PMID 35317721, 2022). "(2018) postulated that the HIF signaling pathway might be used to control the expression of CD248/endosialin in HSC, which would after have an impact on the function of HSC and the onset of liver fibrosis." (PMID 36523459, 2022). "After confirming its binding affinity and specific cytotoxicity toward CD248 positive HSCs in vitro, we verified that IgG78-DM1 could alleviate CCl4-induced liver fibrosis in vivo." (PMID 35317721, 2022). "In this study, we first examined CD248 expression in the liver tissue of patients with hepatic cirrhosis and in carbon tetrachloride (CCl4)-induced liver fibrosis in C57BL/6 mice, and confirmed that CD248 was mainly expressed in alpha smooth actin (α-SMA)+ myofibroblasts." (PMID 35317721, 2022). "The present study demonstrated that CD248 is an ideal target for anti-fibrotic therapy and specific killing of CD248+ myofibroblasts using IgG78-DM1 could be a novel and effective strategy to treat liver fibrosis." (PMID 35317721, 2022). "The role of CD248 in PDGF-BB signaling has been studied in human pericytes and hepatic stellate cells (HSC), commonly considered the precursors of septal myofibroblasts in liver fibrosis." (PMID 30285896, 2018). "The role of CD248 in liver fibrosis has not yet been established, but given its potential role in other fibrotic diseases, we sought to evaluate the function of CD248 in chronic liver injury." (PMID 26078290, 2016). "A CD248-specific antibody-drug conjugate (IgG78-DM1) was generated that could bind specifically with and kill CD248-positive hepatic stellate cells in vitro, could alleviate liver fibrosis in vivo, and had a good safety profile." (PMID 35317721, 2022).
liver fibrosis (continued). "We showed that in an experimental model of liver fibrosis mice lacking CD248 developed less fibrosis, which may be secondary to a decrease in PDGF signal transduction resulting in defective HSC proliferation, and hence reduced ECM deposition." (PMID 26078290, 2016). "Recent studies in hepatic fibrosis, however, have provided evidence that HSC CD248−/− display normal levels of PDGF receptors, suggesting that the antiproliferative effect of CD248−/− HSCs is not mediated through the modulation of PDGF receptor expression." (PMID 30285896, 2018).
renal cell carcinoma (8 papers, 2021 to 2025). "Clinical studies have indicated that CD248 overexpression in the vasculature of renal cell carcinoma patients predicts adverse clinical outcomes." (PMID 40451785, 2025). "In our previous study, we found that CD248 overexpression correlated with an immunosuppressive TME in renal cell carcinoma (RCC), predicting poor prognosis for patients with RCC." (PMID 39334513, 2024). "We also found that overexpression of CD248 in renal cell carcinoma (RCC) was related to poor prognosis." (PMID 34869004, 2021). "In renal cell carcinoma, CD248+ CAFs infiltration may contribute to renal cell carcinoma progression and an immunosuppressive TME through cell‐ ECM interactions and metabolic regulation." (PMID 39164826, 2024).
breast carcinoma (7 papers, 2009 to 2025). "Immunohistochemical staining indicated that CD248 protein expression was upregulated in endometrioid carcinoma subtype of ovarian cancer, in breast lobular carcinoma subtype of breast cancer, as well as in stomach adenocarcinoma." (PMID 40276611, 2025). "Elevated‐CD248 expression also correlated with greater metastasis and poorer survival in human breast cancer patients." (PMID 31287944, 2019). "In independent cohorts of primary human breast cancers, upregulated CD248 expression correlated with increased metastasis." (PMID 30847027, 2019). "Further studies revealed that expression of CD248 exhibited negligible effects on primary tumour growth but increased metastasis formation in mouse models of breast cancer." (PMID 31287944, 2019). "By immunohistochemistry, CD248 co-localized with the pericyte marker NG2 in breast cancer specimens but not with the endothelial marker CD31." (PMID 30847027, 2019).
atherosclerosis (6 papers, 2019 to 2024). A disease characterized by the build-up of fatty material and calcium deposition in the arterial wall resulting in partial or complete occlusion of the arterial lumen. "Atherosclerosis, assessed by descending aorta Oil Red O staining, was reduced in ApoE/CD248-deficient mice." (PMID 30847027, 2019). "Vascular smooth muscle cells played a key role in the pathogenesis of atherosclerosis, while CD248 promoted atherosclerosis by remodeling the phenotype of vascular smooth muscle cells." (PMID 36119065, 2022). "Recently, genetic deletion of CD248 has been shown to protect mice against atherosclerosis on a high fat diet." (PMID 33462674, 2021). "CD248 is expressed in vascular smooth muscle cells (VSMCs) undergoing proliferation and remodelling in apolipoprotein‐E (ApoE) KO mouse models of atherosclerosis as well as atherosclerotic lesions from patients." (PMID 31287944, 2019). "CD248 was upregulated during atherosclerosis in apolipoprotein E (ApoE)– null mice and human atherosclerotic samples." (PMID 30847027, 2019). "CD248 was shown to promote atherosclerosis as ApoE and CD248 double KO mice displayed less atherosclerosis when fed a Western style diet." (PMID 31287944, 2019). "Recently, a role for CD248 in adipocyte accumulation and atherosclerosis has been identified." (PMID 33462674, 2021). "To determine whether CD248 was involved in the formation of atheroma, we previously crossed the CD248 knockout mouse with the ApoE−/− model of atherosclerosis." (PMID 33462674, 2021). "CD248 was a regulator of VSMC phenotypic remodeling contributing to atherosclerosis." (PMID 30847027, 2019). "VSMC expressing CD248 are important in the pathogenesis of atherosclerosis." (PMID 30847027, 2019). "Reduced macrophage recruitment in CD248 KO mice was also shown in other models of inflammation not involving atherosclerosis." (PMID 31287944, 2019).
glioma (6 papers, 2017 to 2024). A benign or malignant brain and spinal cord tumor that arises from glial cells (astrocytes, oligodendrocytes, ependymal cells). "Of note, in a previous study, using laser-capture microdissection and transcriptional analysis, the authors identified CD248 and PDGFRβ, both related to the pericyte phenotype, within upregulated molecules in glioma-associated vessels in comparison to normal vessels." (PMID 34272603, 2021). "By contrast, we observed a slight increase in the CD248 IHC staining, which labels tumor-pericytes in gliomas." (PMID 33147752, 2020). "Moreover, the transcription of CD34, EMCN (another marker of endothelial tumor cells) and CD248 was increased in the GBMwt_hi group compared to the rest of gliomas." (PMID 33147752, 2020). "Notably, only the expression of CD248, was increased in GBMwt_lo tumors compared to IDHmut gliomas, which correlated with the higher CD248 score measured by IHC, suggesting a direct correlation between the absence of IDH mutations and the increase in tumor pericytes, as we have recently described." (PMID 33147752, 2020). "Through interactions with ECs, pericytes overexpress the transmembrane receptor endosialin (CD248 or TEM1), which takes part in maintaining the microvasculature net exclusively in malignant solid tumors, including high-grade gliomas." (PMID 39796646, 2024). "Mixed cell cultures from gliomas expressing high CD56, SOX2, SOX9, and low CD105, CD248, αSMA are tumorigenic and express cancer stem cell markers." (PMID 30847027, 2019). "Glioma-derived pericytes are characterized by the expression of CD90, CD248, and platelet-derived growth factor receptor-β." (PMID 30847027, 2019). "The expression of CD248 on perivascular cells but not on endothelium in vivo was unequivocally demonstrated using multiple fluorescent labelling of human glioma sections." (PMID 31287944, 2019). "Although CD248 is not expressed in normal human adult brain, it is expressed in the angiogenic vasculature of high-grade glioma." (PMID 30847027, 2019).
Obesity (6 papers, 2021 to 2025). Accumulation of substantial excess body fat. "FAP2 cells demonstrated enhanced expression of the genes encoding DPP4 (Dpp4), an adipose stem cell marker that also identifies Cxcl14-negative FAPs, and endosialin (Cd248), an obesity-associated glycoprotein." (PMID 38954467, 2024). "The pericyte specific transmembrane receptor CD248 has been shown to be elevated in adipocytes of insulin‐resistant individuals with obesity." (PMID 40229590, 2025). "Specifically, Cd248-/- mice are protected from obesity and glucose intolerance when fed a high fat diet and the serum lipid profile of Cd248-/- mice on a high fat diet is altered, suggesting differences in lipid synthesis pathways." (PMID 37115796, 2023). "CD248 (Endosialin/Tumour Endothelial Marker 1) has previously been identified as a protein upregulated on mesenchymal cells in a number of human diseases, and recently in obesity." (PMID 33462674, 2021). "Interestingly, hypoxia, inflammation, and fibrosis in obesity could be eliminated by adipocyte-specific CD248 knockdown, which makes CD248 a potential target for improving metabolic health." (PMID 36119065, 2022). "CD248, which has been recently linked with insulin metabolism, NAD(P)H quinone dehydrogenase 1 (NQO1) and tenomodulin (TNMD) were downregulated following LIWL, and expression was reduced in SAT of individuals with or without obesity of the LATC and OA cohorts." (PMID 40229590, 2025). "CD248, which has been recently linked with insulin metabolism, NAD(P)H quinone dehydrogenase 1 (NQO1) and tenomodulin (TNMD) were downregulated following LIWL, and their expression was also reduced in SAT of individuals with or without obesity of the LATC and OA cohort." (PMID 40229590, 2025).
fibrosarcoma (5 papers, 2011 to 2024). A malignant mesenchymal fibroblastic neoplasm affecting the soft tissue and bone. "In another study, tumor cell CD248 expression was seen in 89% of undifferentiated pleomorphic sarcoma (104/117), 77% adult fibrosarcoma/spindle cell sarcoma (20/26), 62% synovial sarcoma (37/60), 51% leiomyosarcoma (94/185) and 31% rhabdomyosarcoma (39/126)." (PMID 30847027, 2019). "We next assessed whether the cytoplasmic domain of CD248 is required for growth of the T241 fibrosarcomas." (PMID 21549007, 2011). "Lastly, tumor cell viability may be affected by loss of CD248 cytoplasmic domain as coculture of WT and cytoplasmic domain-absent CD248 with T241 fibrosarcoma cells resulted in reduced tumor cell viability after 48 h." (PMID 38468017, 2024). "In our studies, we established that the cytoplasmic domain of CD248 is a key regulator of tumor growth and that mice lacking this domain are resistant to growth of T241 fibrosarcoma tumors and heterotopic LLC tumors." (PMID 21549007, 2011). "Since CD248 is not expressed by tumor cells, but rather by activated fibroblasts, it is interesting to note that conditioned media from CD248CyD/CyD fibroblasts dampened the proliferative potential of T241 fibrosarcoma cells." (PMID 21549007, 2011).
heart failure (5 papers, 2022 to 2024). Inability of the heart to pump blood at an adequate rate to meet tissue metabolic requirements. "However, the initial active player M_SH, co-expressing Ackr3, Cd34, Cd248, and Pi16, was reported as cardiac mesenchymal-like stem cells with multilineage differentiation and self-renewal capacities, and promoted heart failure." (PMID 37147443, 2023).
rheumatoid arthritis (5 papers, 2011 to 2023). A chronic, systemic autoimmune disorder characterized by inflammation in the synovial membranes and articular surfaces. "In the lining layer in rheumatoid arthritis, synovial fibroblasts expressed higher podoplanin than normal synovium, and CD248 expression was restricted to sub-lining layer cells." (PMID 30847027, 2019). "CD248 knockout produced high bone mass due to increased osteoblast-mediated bone formation, suggesting targeting CD248 in rheumatoid arthritis." (PMID 30847027, 2019). "We recently demonstrated that the highly conserved cytoplasmic domain of CD248 mediates signals that regulate stromal fibroblast function in an experimental model of rheumatoid arthritis and hypothesized that it would play a similarly important role in modulating tumor growth." (PMID 21549007, 2011). "We analyzed the regulated expression of CD248 in vitro using skin (HFFF) and synovial (FLS) mesenchymal stem cell lines, and in fluid and tissue samples of rheumatoid arthritis (RA) and osteoarthritis (OA) patients." (PMID 37298499, 2023). "SF in the lining layer in rheumatoid arthritis (RA) expressed high levels of PDPN compared to the normal synovium, whereas CD248 expression was restricted to sub-lining layer cells." (PMID 27863512, 2016).
brain tumors (4 papers, 2009 to 2024). "In a recent analysis of brain tumor biopsies, we found a strong expression of CD248 in highly invasive glioblastoma multiforme, high-grade astrocytomas, and metastatic carcinomas." (PMID 37298499, 2023).
colon carcinoma (4 papers, 2009 to 2024). "Drug resistance of colon cancer cells can be effectively reversed by transfection of miR-125b-5p mimics or silencing of Sp1 or CD248 genes." (PMID 39867908, 2024). "In chemoresistant colon cancer cells, upregulation of TLR2/6 and TLR5 result in downregulation of miR-125b-5p and upregulation of CD248 through NF-κB activation of specific protein 1 (Sp1)." (PMID 39867908, 2024).
glioblastoma (4 papers, 2009 to 2022). The most malignant astrocytic tumor (WHO grade IV). "Later, CD248 was found to be expressed in the vasculature and fibroblasts of human brain tumor specimens, including astrocytoma, anaplastic astrocytoma, glioblastoma multiforme, meningioma, oligodendroglioma, ependymoma and carcinoma brain metastasis." (PMID 30847027, 2019).
non-small cell lung carcinoma (4 papers, 2009 to 2025). A group of at least three distinct histological types of lung cancer, including non-small cell squamous cell carcinoma, adenocarcinoma, and large cell carcinoma. "CXCL12, derived from CD248-expressing cancer-associated fibroblasts, mediated M2-polarized macrophages to promote non-small cell lung cancer progression." (PMID 38232115, 2024).
aortic aneurysm (3 papers, 2024 to 2025). A ruptured aneurysm located in the wall of the proximal portion of the descending aorta proceeding from the arch of the aorta. "In this study, we reported a dramatic upregulation of CD248 in aortic aneurysms of humans and mice, and showed that genetic deletion of Cd248 exacerbated Ang II‐induced aortic lesion in mice." (PMID 40415469, 2025). "In contrast, CD248 expression was significantly increased in the medial smooth muscle and adventitial fibroblast layers of patients with aortic aneurysm, despite minimal VSMCs in advanced stage aneurysmal tissues." (PMID 40415469, 2025). "CD248 expression was upregulated in the media and adventitia of patients and mice with aortic aneurysm." (PMID 40415469, 2025). "Thus, the increased expression and stability of CD248 in the plasma membrane, as well as the potentiation of its downstream signalling, highlight a potential therapeutic approach for aortic aneurysm." (PMID 40415469, 2025). "Therefore, we hypothesized that CD248 participates in the progression of aortic aneurysms due to its pleiotropic nature in coordinating several membrane receptors." (PMID 40415469, 2025). "Thus, upregulated expression of CD248 in human and mouse aortic lesion suggests that CD248 may participate in aortic aneurysm formation and progression." (PMID 40415469, 2025). "To explore whether CD248 is involved in the pathophysiology of aortic aneurysms, we first investigated its expression in patients with aortic aneurysm and compared Ang II (1000 ng/kg/min)‐infused mice fed a high‐cholesterol diet (Ang II+Chol) against untreated conrtol mice." (PMID 40415469, 2025).
fibrosis (3 papers, 2016 to 2018). the formation of excess fibrous connective tissue in an organ or tissue in a reparative or reactive process. "Importantly, our study demonstrates that interfering with CD248 signalling significantly reduces hepatic fibrosis in a mouse model of chronic liver disease." (PMID 26078290, 2016). "Recently, CD248 has been considered as a marker of stromal fibroblasts, pericyte subsets, and human MSC, and in the experimental model of fibrosis, after UUO, a significant upregulation of CD248 was observed." (PMID 30285896, 2018).
metastatic melanoma (3 papers, 2021 to 2024). A melanoma that has spread from its primary site to another anatomic site. "Interestingly, CD248 has been reported to play a role in tumor vasculature and was expressed in 86% of metastatic melanoma samples analyzed by tumor microarrays." (PMID 38732242, 2024). "Whether CD248 and CSPG4 could be optimal antigen targets for metastatic melanoma in CAR-T cell therapy remains to be validated." (PMID 38732242, 2024). "Studies have shown that CD248 is expressed in 86% of metastatic melanoma specimens using tumor microarrays, with no expression in healthy tissues." (PMID 34207884, 2021). "Thus, CD248 could be a useful and safe antigen for CAR T cell therapy in metastatic melanoma patients." (PMID 34207884, 2021).
pulmonary fibrosis (3 papers, 2016 to 2022). Chronic progressive interstitial lung disorder characterized by the replacement of the lung tissue by connective tissue, leading to progressive dyspnea, respiratory failure, or right heart failure. "This study investigates the role of CD248 in the pathogenesis of fibrotic diseases in Idiopathic Pulmonary Fibrosis (IPF)." (PMID 27080864, 2016). "In pulmonary fibrosis we observed elevated CD248 expression." (PMID 27080864, 2016). "Indeed, our MSC fibroblast-like cells expressing the canonical markers CD248 and CD90 were able to differentiate into myofibroblast key effector cells of pulmonary fibrosis." (PMID 36552855, 2022).